NOP14 (NOP14 nucleolar protein)
Diseases named in the same sentence as NOP14 in open-access papers (continued):
Sharing a sentence is not in itself a finding about the gene and the disease.
cancer (9 papers, 2015 to 2024). A tumor composed of atypical neoplastic, often pleomorphic cells that invade other tissues. "Human NOP14 has been reported to play oncogenic roles in human cancer; however, the underlying molecular mechanism beyond ribosome biogenesis remains unclear." (PMID 38272224, 2024). "NOP14, which is functionally conserved among eukaryotes, has been implicated in cancer development." (PMID 26213846, 2015). "In this report, we show that human NOP14, a 40S ribosome biogenesis factor whose expression is upregulated in cancer cells, plays a pivotal role in mTORC2-Akt signaling by creating ribosome-coated ER as a platform for mTORC2 activation." (PMID 38272224, 2024). "Recently, studies regarding the influence of nucleolar complex protein 14 (NOP14) on cancers have been conducted, and this protein has been shown to play an important role in cancer migration and invasion." (PMID 37441804, 2023). "By applying diverse proteomic and biochemical methods we investigated the cellular mechanism of vioprolide A (VioA) in Jurkat cancer cells and recovered nucleolar protein 14 (NOP14), which is essential for ribosome biogenesis, to be a specific target." (PMID 31658409, 2020). "Moreover, Oncomine expression analysis indicated high NOP14 expression in other human cancer types, suggesting that elevated NOP14 expression is a characteristic feature of multiple human cancer types." (PMID 38272224, 2024). "Notably, cancer cells with NOP14 high expression exhibit increased sensitivity to mTOR inhibitors, because the feedback activation of the PI3K-PDK1-Akt axis by mTORC1 inhibition was compensated by mTORC2 inhibition partly through NOP14 downregulation." (PMID 38272224, 2024). "Therefore, NOP14 has a dual function of promoting or inhibiting tumors and plays disparate roles in various cancers by regulating diverse downstream pathways." (PMID 37506248, 2023). "Furthermore, we studied the effect of NOP14 dysregulation on cancer cell proliferation and investigated its potential mechanism." (PMID 37506248, 2023). "Nonetheless, the roles of NOP14 varies depending on the specific types of cancer." (PMID 35473611, 2022). "Nucleolar protein 14 (NOP14) is known to play different roles in diverse types of cancers." (PMID 35473611, 2022). "The involvement of NOP14 in cancer initiation and development is still unclear." (PMID 35473611, 2022). "Similarly, NOP14 protein expression level was significantly higher in cancer tissues than in normal tissue samples according to the data from UALCAN." (PMID 35473611, 2022). "Indeed, inhibition of PI3K/Akt/mTOR abolished the advantages of NOP14 on cancer cell proliferation, colony formation in soft agar, cell migration, and tumor growth in an in vivo NPC xenograft model, consistent with the finding that NOP14 expression is mTOR dependent." (PMID 38272224, 2024). "However, the subcellular localization of NOP14 in cancer cells has rarely been reported." (PMID 37506248, 2023). "However, the function and molecular mechanism of NOP14 remain ambiguous in most human cancers." (PMID 37506248, 2023). "Moreover, increasing studies supported that NOP14 is involved in cancer initiation and development." (PMID 35473611, 2022). "Importantly, knockdown of NOP14 impairs cancer‐cell proliferation for VioA." (PMID 31658409, 2020). "Recent studies have suggested that NOP14 may be involved in cancer development." (PMID 26213846, 2015). "Among the differentially expressed genes in primary samples, 7 of 39 genes (VHL, GNE, POLH, MAPK13, NOP14, INADL, CDC5L) were reported to be cancer-related in the literature." (PMID 28009993, 2017). "NOP14 was observed to be upregulated in most NPC cells when compared to normal nasopharyngeal epithelial cells, with the highest levels of expression noted in 5-8F and 6-10B cancer cells." (PMID 38272224, 2024).
cancer (continued). "Given the role of NOP14 in mTORC2 activation, we then sought to determine whether NOP14 levels could serve as an indicator of the responsiveness to PI3K/mTOR inhibitors in cancer cells." (PMID 38272224, 2024). "Subsequent cell proliferation assays showed that the proliferation was enhanced or inhibited significantly after upregulation or downregulation of NOP14, respectively, in PANC1, indicating that NOP14 played a dominant role in promoting cancer cell proliferation." (PMID 37506248, 2023). "Then, a CDM signature with five cancer-dependent genes (MMS19, NOP14, POLRMT, SNAPC5 and TIGD1) and a prognostic nomogram were constructed, and they demonstrated robust predictive performance and a close relationship with clinical characteristics in different CC datasets." (PMID 37441804, 2023).
tumor (8 papers, 2015 to 2025). "The results of GSEA revealed that some pathways associated with tumor cell growth were significantly enriched in NOP14 low- expression group (p < 0.05, FDR < 0.025), e.g., FORMATION_OF_THE_BETA_CATENIN_TCF_TRANSACTIVATING_COMPLEX, DNA_METHYLATION, SIGNALING_BY_NOTCH." (PMID 35473611, 2022). "mentioned that NOP14 is important in cell proliferation, cell metastasis, cell apoptosis and other tumor progression is important." (PMID 39963131, 2025). "To date, few studies have addressed the relationship between abnormal expression of NOP14 and tumor development." (PMID 37506248, 2023). "Altogether, these results indicated that high NOP14 expression leads to improved prognosis in CRC patients by inhibiting the signaling pathways involved in tumor growth and promoting the immune responses." (PMID 35473611, 2022). "We found that NOP14 interacted with some proteins closely related to tumor initiation and development, such as BYSL or NOL6." (PMID 35473611, 2022). "Xenograft model showed that knockdown of NOP14 by shRNA #4 (7 of 7 mice) resulted in larger and heavier tumor formation than that of the mock transfected (6 of 7 mice)." (PMID 26213846, 2015). "Consistent with our results in TCGA, the immunohistochemistry results of the HPA database presented that the protein expression level of NOP14 was elevated in the tumor cells compared with the corresponding glandular cells, and mainly localized to the cytoplasmic and membranous nuclear." (PMID 36911744, 2023). "In this study, we found that Wnt/β-catenin signal pathway was enriched in NOP14 low expression group, indicating that high NOP14 expression might downregulate the pathway, acting as a tumor suppressor gene." (PMID 35473611, 2022). "Altogether, these results suggest that NOP14 may exert an anti- oncogenic function by triggering anti-tumor immune responses in CRC tissues." (PMID 35473611, 2022). "For example, NOP14 inhibited the Wnt/β-catenin signaling pathway, which reduced the proliferation and metastasis of melanoma and breast cancer, thereby acting as a tumor suppressor gene." (PMID 35473611, 2022). "In this sense, NOP14 might have an important role in tumor development and progression." (PMID 37506248, 2023). "Therefore, NOP14 might act as a tumor suppressor gene through inhibiting some tumor growth-related signal pathways in CRC cells, such as Wnt/β-catenin pathway." (PMID 35473611, 2022). "Interestingly, the inhibitions of cell migration and tumor metastasis by NOP14 were shown to be NRIP1-dependent, indicating that NRIP1 might be a major effector transducing NOP14 signaling." (PMID 26213846, 2015). "NOP14 expression levels were positively correlated with numerous types of immune cells, e.g., Th2 cells, CD8 T cells, T helper cells, NKCD56 dim cells, NK cells, and aDC cells, all of which play an important role in anti-tumor immunity." (PMID 35473611, 2022). "In addition, NOP14 induced expression of transcription factor E2F4 independent of miR17-5p/P130 signaling, which simultaneously activated a set of targeted genes, such as CCNE1, PIM1, AKT1 etc., to promote tumor proliferation." (PMID 37506248, 2023). "However, the functional localization of NOP14 in human malignant tumor cells has not been reported." (PMID 37506248, 2023). "In this study, we found that NOP14 expression levels were positively correlated to the infiltration levels of numerous immune cells, such as CD8 cells, CD4 cells, NK cells, and dendritic cells, suggesting that NOP14 might promote the anti-tumor immune response in tumor tissues." (PMID 35473611, 2022).
tumor (continued). "Additionally, NOP14 expression levels were significantly correlated with the expression levels of many immune molecules, like MHC genes, immune activation genes, chemokine receptor, and chemokines, which might recruit immune cell infiltration, thereby exerting an anti-tumor effect." (PMID 35473611, 2022).
infection (1 paper, 2024). The state of being infected such as from the introduction of a foreign agent such as serum, vaccine, antigenic substance or organism. "In line with the overexpression data, knockdown of NOP14 dramatically reduced cell proliferation, and most cells died 1 one week after lentiviral shRNA infection; accordingly, the knockdown cells were unable to form colonies." (PMID 38272224, 2024).
NOP14 also shares sentences with these, for which no sentence is quoted: colon cancer (3 papers); breast fibrocystic disease (1); cholangiocarcinoma (1); hepatocellular carcinoma (1); lung adenocarcinoma (1); medulloblastoma (1); migraine (1); neuroblastoma (1); nevus (1); rectal cancer (1); rectum adenocarcinoma (1); sarcoma (1); stomach adenocarcinoma (1).